CTSB (cathepsin B)
Description:
Thiol protease which is believed to participate in intracellular degradation and turnover of proteins. Cleaves matrix extracellular phosphoglycoprotein MEPE. Involved in the solubilization of cross-linked TG/thyroglobulin in the thyroid follicle lumen (By similarity). Has also been implicated in tumor invasion and metastasis.
Synonyms: APPS; CPSB; KWE; RECEUP
Tractability: Small molecule: a structure with a bound ligand is known; a high-quality ligand is known; it has a high-quality binding pocket; it belongs to a druggable protein family. Antibody: its Gene Ontology location is reachable by antibodies, with high confidence; UniProt places it where antibodies can reach, with medium confidence; UniProt predicts a signal peptide or a membrane-spanning region. PROTAC: ubiquitination databases record sites on it; its protein half-life has been measured; a small molecule that binds it is known.
Target class: Cysteine protease; Cysteine protease CA clan; Enzyme; Protease; Cysteine protease C1A family
Gene: Protein-coding gene on chromosome 8 (11,842,524 to 11,869,533, reverse strand). Ensembl gene ENSG00000164733.
Subcellular location: Lysosome; Melanosome; Secreted, extracellular space; Apical cell membrane
Subcellular location (Human Protein Atlas): Vesicles; Nucleoli; Predicted to be secreted
Pathways (Reactome):
Immune System: MHC class II antigen presentation; Neutrophil degranulation; Trafficking and processing of endosomal TLR
Cell-Cell communication: Degradation of CDH1; SRC activates STAT3 in a quantitative manner, through Cadherin-11 (CDH11), RAC1 and gp130 (IL6ST)
Extracellular matrix organization: Assembly of collagen fibrils and other multimeric structures; Collagen degradation
Gene Ontology:
Molecular function: collagen binding; cysteine-type endopeptidase activity; cysteine-type peptidase activity; peptidase activity; protein binding; proteoglycan binding; endopeptidase activity
Biological process: cellular response to thyroid hormone stimulus; collagen catabolic process; epithelial cell differentiation; protein catabolic process; proteolysis; regulation of apoptotic process; symbiont entry into host cell; thyroid hormone generation
Cellular component: extracellular exosome; extracellular matrix; extracellular region; lysosome; melanosome; peptidase inhibitor complex; perinuclear region of cytoplasm; apical plasma membrane; endolysosome lumen; ficolin-1-rich granule lumen; external side of plasma membrane
Genetic constraint (gnomAD): Loss-of-function variants: 56 observed, 39.68 expected, observed/expected ratio (o/e) 1.41, 90% interval 1.14 to 1.76. The synonymous counts are far from expectation, so gnomAD's model fits this gene poorly and the ratio says little. Missense variants: 732 observed, 434.96 expected, observed/expected ratio (o/e) 1.68, 90% interval 1.58 to 1.79. Synonymous variants: 311 observed, 167.82 expected, observed/expected ratio (o/e) 1.85, 90% interval 1.68 to 1.97.
Homologues: Orthologues: chimpanzee CTSB (99% identical), macaque CTSB (97% identical), guinea pig CTSB (82% identical), dog CTSB (81% identical), pig CTSB (80% identical), mouse Ctsb (79% identical), rat Ctsb (79% identical), rabbit CTSB (76% identical), tropical clawed frog ctsb (70% identical), zebrafish ctsba (70% identical), Caenorhabditis elegans cpr-5 (47% identical), Caenorhabditis elegans cpr-1 (46% identical), and 11 more. Paralogues in human: CTSC (32% identical), TINAGL1 (27% identical), CTSV (24% identical), CTSH (23% identical), CTSK (23% identical), CTSS (23% identical), CTSZ (23% identical), TINAG (22% identical), CTSL (22% identical), CTSW (20% identical), CTSF (18% identical), CTSO (18% identical).
Diseases named in the same sentence as CTSB in open-access papers:
CTSB is named in the same sentence as 457 diseases in open-access papers, as found by Europe PMC text mining. Sharing a sentence is not in itself a finding about the gene and the disease. The quoted sentences say what the papers report.
breast carcinoma (103 papers, 2004 to 2025). "In a murine breast cancer model, nanocomplexes releasing pro-apoptotic peptides in response to tumour-associated cathepsin B significantly improved the efficacy of doxorubicin, reducing tumour growth by up to 91%." (PMID 40724272, 2025). "CTSD and CTSB, two aspartic proteases, have been linked with tumourigenesis and worse therapy response in breast cancer and glioblastoma." (PMID 39187937, 2024). "In breast cancer, increased expression of cathepsin B and cathepsin L is associated with poorer prognosis, greater mortality, and greater disease metastases." (PMID 38026637, 2023). "Several underlying molecular mechanisms of cathepsin B overexpression and its contribution to cancer progression have been elucidated, some of which seem to be breast cancer subtype-specific." (PMID 36002710, 2023). "Cathepsin B has been implicated in diseases such as Alzheimer’s disease, some cancers including brain and breast cancers, pancreatitis, and arthritis." (PMID 37037462, 2023). "In in vitro assays, the Al-ProD efficiently bound to three types of albumin (HSA, BSA, MSA) and induced 30-fold strong cytotoxicity in cathepsin B-overexpressed MDA-MB231 breast cancer cells compared to cathepsin B-deficient H9C2 cardiomyocytes." (PMID 35456562, 2022). "In the MMTV-PyMT model of metastasizing breast cancer, the transgenic expression of human CTSB is associated with faster tumor growth, enlarged tumor size, increased number and size of metastasis, and higher grade of malignancy." (PMID 32385587, 2021). "Cathepsin X has been shown to promote cancer growth and invasion by compensation for cathepsin B proteolytic activity in the cathepsin B-deficient transgenic polyoma middle T oncogene (PymT)-induced breast cancer mouse model." (PMID 30046941, 2018). "We have demonstrated that SAHA is capable of inducing several apoptosis and autophagy-related genes expression associated with the increased expression of CTSB in breast cancer MDA-MB-231 and MCF-7 cells." (PMID 28881816, 2017). "For instance, cathepsin B (CTSB gene, reported as mutated in our study) inhibition has been reported as associated with reduced bone metastasis in breast cancer from mice." (PMID 28402931, 2017). "In CTSB-deficient mice, tumor cell proliferation was decreased, disrupting high-grade mammary carcinoma development." (PMID 27031837, 2016). "IL-6 has previously been shown to upregulate cathepsin B, a protease associated with breast cancer progression." (PMID 26268945, 2015). "It has been reported that CTSB was a downstream target of hedgehog signaling in breast cancer and hedgehog signaling activated CTSB was associated with tumor invasion." (PMID 24139065, 2013). "Cathepsin B has been linked to both pericellular and intracellular proteolysis in breast cancer cells." (PMID 22093547, 2011). "In vivo studies also provide evidence for an association between cathepsin B and breast cancers that are triple negative (N Withana, BF Sloane and BS Parker, unpublished observations)." (PMID 22093547, 2011). "Dysregulated CTSB expression is implicated in cancers, where it enhances tumor invasion and metastasis by degrading extracellular matrix components, serving as a prognostic biomarker in breast cancer and gliomas." (PMID 40943452, 2025). "For example, elevated CTSB is associated with increased immune cell infiltration of tumor-associated B cells and mast cells, and facilitates progression and metastasis of PymT-induced mammary carcinomas." (PMID 34923982, 2021). "Indeed, analysis of cathepsin B/Z double-deficient mice in the context of the MMTV-PyMT breast cancer model revealed a strongly reduced tumor and lung metastatic burden, while a single cathepsin Z deficiency had no clear effect on the overall tumor phenotype." (PMID 22798952, 2012).
breast carcinoma (continued). "Moreover, cathepsin × neutralizing antibodies reduced invasion of the cathepsin B-deficient mammary tumor cells, a result that is consistent with cathepsin × compensating for the absence of cathepsin B." (PMID 22093547, 2011). "A striking example is the redistribution of active cathepsin × to the surface of mammary tumor cells isolated from mice deficient in cathepsin B that had been crossed with mice predisposed to develop mammary cancer, in this case MMTV-PyMT transgenic female mice." (PMID 22093547, 2011). "Moreover in an animal mammary cancer model, the number of positive metastatic lymph nodes has also been found to be associated with expression of CTSB." (PMID 21199580, 2011). "The protease cathepsin B (CTSB) has been identified to highly express in cancer, and associate with poor prognosis of a variety of cancers, including breast cancer, pancreatic cancer, and lung squamous cell carcinoma, which could be used as an independent predictor of these tumors." (PMID 33708242, 2021). "Semi-quantitative analysis of the stained breast cancer tissues showed all tumors had cathepsin B, L, and/or S expression to some extent (TIS > 0) and expression levels of cathepsin B, L, and S were high (TIS > 6) in 28%, 80%, and 18% of cases, respectively." (PMID 39331316, 2024). "In breast cancer, melanoma, and lung cancer, heightened cathepsin B activity has been correlated with increased tumour invasion and metastasis." (PMID 38500921, 2024). "Most of the existing cathepsin-activatable fluorescent imaging agents are directed against cathepsin B, L, and/or S. Therefore, this immunohistochemical study investigated the expression of these cathepsins in TMAs of a large cohort of breast cancer patients." (PMID 39331316, 2024). "Cathepsin B was reported to promote the cytotoxicity of HER2-targeted antibody-drug conjugates in breast cancer." (PMID 38360722, 2024). "The cellular sources of cathepsin B in breast cancer are predominantly tumor cells and macrophages and, to a lesser extent, stromal components such as myoepithelial cells, fibroblasts, myofibroblasts, and endothelial cells of the neo-vasculature." (PMID 36002710, 2023). "CST6 protein and peptides limit bone metastases in breast cancer by reducing CTSB activity and osteoclastogenesis." (PMID 37377916, 2023). "In human epidermal growth factor receptor 2 (HER2)-positive breast cancer, for instance, overexpression is the result of an increased transcription of the cathepsin B gene due to an HER2-activated kinase signaling network." (PMID 36002710, 2023). "In conclusion, cathepsin B is upregulated in various breast cancer subtypes and has a broad spectrum of cellular sources at the primary and metastatic site." (PMID 36002710, 2023). "Cathepsin B is one of the more ubiquitously expressed members of the cysteine cathepsin family that has been a main focus of research in breast cancer." (PMID 36002710, 2023). "The important contribution of cathepsin B to breast cancer progression becomes clear in cell line and murine model studies." (PMID 36002710, 2023). "Both inflammatory breast cancer cell lines and patient samples show elevated levels of cathepsin B, with the latter displaying a positive correlation with the number of lymph node metastases." (PMID 36002710, 2023). "For example, in transgenic mouse models of pancreatic duct adenocarcinoma, breast cancer cells, and myeloid-derived suppressor cells, reduced expression of cathepsin B was compensated by cathepsin X/Z in breast cancer cells." (PMID 36552871, 2022). "We found CTSB in CUPsig was a target of Trastuzumab deruxtecan, which had been approved for certain types of metastatic or unresectable breast cancer." (PMID 36293319, 2022). "High CTSB expression has been associated with suberoylanilide hydroxamic acid (SAHA)-induced autophagy, which suppresses breast cancer growth." (PMID 35459137, 2022).
breast carcinoma (continued). "On the other hand, reduced CtsB expression has been shown to reduce glioma, osteosarcoma, and mammary cancer cell malignancy, while a low StfA expression was associated with glioblastoma, breast, and head and neck cancer progression." (PMID 35563761, 2022). "A higher CtsB expression in mammary cancer cells increased cell division, while its silencing in glioblastoma inhibited cell proliferation, reducing the levels of pERK and pFAK." (PMID 35563761, 2022). "Positive staining was demonstrated on human tissues: placenta for cathepsin B, breast carcinoma for cathepsin D and tonsil for cathepsin G." (PMID 34409065, 2021). "Previous clinical and experimental evidence strongly supports a breast cancer-promoting function of the lysosomal protease cathepsin B. However, the cathepsin B-dependent molecular pathways are not completely understood." (PMID 32385587, 2021). "Human tissues used for positive controls demonstrated the expected staining patterns for cathepsin B on placenta, cathepsin D on breast carcinoma, cathepsin G on tonsil." (PMID 34621666, 2021). "Previous studies have found that the overexpression of cathepsin B leads to the invasiveness and metastasis of breast cancer, pancreatic cancer, HCC, and colorectal cancer, by activating the ErbB oncogenic signaling pathway." (PMID 34272452, 2021). "Selective action of Al-ProD was studied in breast cancer cells and cardiomyocytes, indicating differential levels of cathepsin B. The in vivo pharmacokinetics and tumor regression effect with minimal toxicity were also carried out in breast cancer models." (PMID 35056979, 2021). "The in vitro selective activation of Al-ProD premised on differential expression levels of cathepsin B was assessed in breast cancer cells (MDA-MB231) and rat BDIX cardiomyocytes (H9C2)." (PMID 35056979, 2021). "These screens were complemented by proteome analysis of tumor interstitial fluid (TIF) derived from MMTV-PyMT primary breast cancers with graded CTSB and CTSZ expression levels." (PMID 32385587, 2021). "The CTSB–CREG1 axis explains at least in part the frequently reported tumor attenuation upon CTSB knock-out or inhibition in MMTV-PyMT breast cancers and other cancer models." (PMID 32385587, 2021). "Cathepsin B is an endopeptidase, whose increased levels were documented in many cancers, for example, in gliomas, melanomas, prostate cancer, and breast cancer." (PMID 33918514, 2021). "The overexpression of cathepsin B promotes invasion and metastasis of breast cancer, pancreatic cancer, HCC, and colorectal cancer." (PMID 34272452, 2021). "Conversely, in a gain-of-function approach utilizing transgenic mice overexpressing human CTSB in breast cancer, we observed a reduced abundance of CREG1 in TIF." (PMID 32385587, 2021). "It has also been found that downregulating of cathepsin B expression in mouse breast cancer models can inhibit type I collagen degradation and bone metastasis." (PMID 32727598, 2020). "Some previous studies reported that the cathepsin B (CTSB) gene was highly expressed in gastric cancer, esophageal cancer, glioma, prostate cancer, and breast cancer tissues, and the expression of the CTSB gene was upregulated at the gene and protein levels." (PMID 33238959, 2020). "In a mouse breast cancer model, the downregulation of shRNA in the expression of the CTSB gene reduced the degradation of type I collagen and inhibited bone metastasis." (PMID 33238959, 2020). "The study found that the expression and activation of cathepsin B were both upregulated in breast cancer, lung cancer, melanoma, gastric cancer, colon cancer and other malignant tumors." (PMID 32727598, 2020). "The overexpression of cathepsin B promoted the invasiveness and progression of breast cancer cells, while downregulation of cathepsin B function by shRNA significantly reduced bone metastasis in mice breast cancer models." (PMID 32999282, 2020).
breast carcinoma (continued). "In stationary breast carcinoma cells, the localization of cathepsin B is perinuclear, but it is concentrated on one side of the nucleus in a moving cell." (PMID 31736973, 2019). "The downregulation of CtsB using synthetic inhibitors such as CA-074 inhibited the neovascularization and the formation of bone metastases in breast cancer." (PMID 31340550, 2019). "Even though the sample number was low, out of the researched tumor-entities, breast cancer showed a significant reduction in cathepsin B mRNA expression compared to healthy tissue." (PMID 31484396, 2019). "Although CTSS expression was much higher than the expression of other cathepsins in TNBC cells, previous studies have shown that CTSB or CTSL regulates breast cancer invasion." (PMID 30185799, 2018). "This study is the first study to clarify the SAHA functions in autophagy through effective regulations of TRAIL DR5 and CTSB and thereby inhibit the proliferation of breast cancer cells and hinder the occurrence of breast cancer." (PMID 29018571, 2017). "We confirmed that Cystatin C, a protease inhibitor, significantly inhibited the expression of CTSB induced by SAHA on breast cancer cells." (PMID 28881816, 2017). "This phenomenon indicates that CTSB is potentially involved in the action of SAHA on breast cancer cells." (PMID 28881816, 2017). "Cystatin C, a protease inhibitor, significantly inhibited the expression of CTSB induced by SAHA on breast cancer cells." (PMID 28881816, 2017). "Western blot and ELISA results indicated that TRAIL DR5 was involved in the expression of CTSB in SAHA-induced breast cancer cells." (PMID 29018571, 2017). "To further explore the molecular mechanisms in the action of SAHA and CTSB in breast cancer cells, we used real-time PCR arrays to determine the expression levels of the genes." (PMID 28881816, 2017). "Results indicated that SAHA did indeed repress the growth of breast cancer cell lines with inducing CTSB expression." (PMID 29018571, 2017). "Our previous studies have demonstrated that CTSB plays an important role in SAHA-induced autophagy of breast cancer cells." (PMID 29018571, 2017). "It is implied that there has a balance between breast cancer invasion and death, possibly involving in CTSB regulation." (PMID 28881816, 2017). "Western blot analysis showed that the protein expression of CTSB was increased in SAHA-treated breast cancer cells." (PMID 29018571, 2017). "To further confirm the effects of SAHA induced CTSB on breast cancer cells, we determined the apoptosis, cell viability and cell growth in MDA-MB-231 and MCF-7 cell lines by using Muse flow cytometry." (PMID 28881816, 2017). "Overall, our results revealed that the autophagy-related genes are induced by SAHA via the activation of CTSB in breast cancer cells." (PMID 28881816, 2017). "In order to investigate the impacts of SAHA induced CTSB on autophagy in breast cancer cells, we checked LC3II in the cells treated with SAHA and Cystain C using laser scanning confocal microscopy." (PMID 28881816, 2017). "In support of the pro-tumorigenic function of cathepsin B, the transgenic expression of human Ctsb promoted progression and metastasis in the same mammary cancer transgenic model." (PMID 29088746, 2017). "For example, the ablation of cathepsin B (Ctsb) in the PyMT model resulted in a significant decrease in mammary tumor growth and volume." (PMID 29088746, 2017). "Cathepsin D, an aspartic protease, is considered to be a candidate as a clinical marker for breast cancer, and is involved in the activation of the inactive form of cathepsin B (procathepsin B)." (PMID 27657126, 2016). "Cathepsin B is essential for the growth of breast cancer and its down-regulation leads to a reduction of tumor progression." (PMID 27657126, 2016). "We demonstrate inhibition by a dipeptidyl nitrile inhibitor (compound 1) of cathepsin B activity and also of pericellular degradation of dye-quenched collagen IV by living breast cancer cells." (PMID 26562785, 2015).